BCL2 (BCL2 apoptosis regulator)
Diseases named in the same sentence as BCL2 in open-access papers (continued):
Sharing a sentence is not in itself a finding about the gene and the disease.
cancer (continued). "The senescent cell eliminators ABT737 and ABT263 are BH3 mimetic inhibitors of antiapoptotic proteins (Bcl-xL, Bcl-2, and Bcl-w) originally developed for cancer therapy; however, the inhibition of Bcl-xL was found to have serious side effects." (PMID 35742971, 2022). "The resistance conferred by Bcl-2 represents an attractive therapeutic strategy for cancer, demonstrating that HS-1793 overcomes the resistance conferred by Bcl-2." (PMID 36430164, 2022). "SS can be suggested as a potential agent in BC cancer treatment or as an adjuvant based on its ability to decrease the expression of Bcl-2 and BCL-XL genes and induce apoptosis." (PMID 35725497, 2022). "Our findings agreed with a recent study that found that cancer cells treated with pure Ap or Ap-loaded PLGA had decreased Bcl-2 protein expression." (PMID 35745733, 2022). "Dysregulation of MCL1 and Bcl2 is noted in cancers and correlates with worse clinical outcomes, thereby rendering them excellent treatment targets." (PMID 35581670, 2022). "Overcoming apoptosis resistance afforded by the expression of Bcl-2 in cancer cells has been an area of intense research." (PMID 36539401, 2022). "In human cancers, the anti-apoptotic proteins (e.g. Bcl-2, Bcl-XL, and Mcl1) are often upregulated in cancer cells, enabling them to evade apoptotic cell death and losing the capacity to undergo apoptosis in response to chemotherapeutic drugs." (PMID 35532120, 2022). "IDH1/2mt cancers are sensitive to BCL2 inhibition because D-2-HG accumulation induces BCL2 dependence via inhibition of cytochrome c oxidase, also known as complex IV of the electron transport chain." (PMID 34967233, 2022). "Since Bcl-2 inhibition and mTORC 1/2 inhibition are synergistic for cancer treatment, we investigated ABT-263 alone and in combination with an mTORC 1/2 inhibitor, TAK-228 (sapanisertib)." (PMID 35643815, 2022). "miR-34a-m@ZIF-8 induces cancer cell apoptosis by suppressing the Bcl-2 expression levels and inhibits the tumor growth in of triple-negative breast cancer mouse model." (PMID 36434667, 2022). "According to our results, surprisingly, cancer-prone species showed the amplification of miR-15 tumor suppressor, which is known to be able to regulate cancer proliferation initiation by targeting the BCL2 gene." (PMID 35741808, 2022). "Further, we validated the anti-cancer and anti-BCL-2 effects of all 29 compounds from a focused library via in vitro and in vivo assays and identified drug-like BCL-2-selective inhibitors." (PMID 36358660, 2022). "VDAC1 has also been found to be involved in anti-apoptosis by interacting with anti-apoptotic proteins overexpressed in cancer such as Bcl-2, Bcl-xL, HK, and mediating the release of Cytc to prevent the cancer cells from apoptosis." (PMID 35729567, 2022). "As another concern, many traditional medicines suppress cancer cells primarily depending on the BCL-2/BAX mechanism." (PMID 36230771, 2022). "After affecting the PI3K/Akt pathways, ILTPs also influence Bcl-2, NF-κB, and caspase-9 expression, thereby promoting cancer cell apoptosis." (PMID 35321703, 2022). "It is possible that the ratio between pro- and anti-apoptotic proteins and the specific dependency on Bcl-2 for cancer cell survival permits the establishment of a therapeutic index and safe targeting of Bcl-2." (PMID 35056993, 2022). "Bcl-2 is extensively considered a therapeutic target for apoptosis-inducing anticancer approaches as it is often overexpressed in many cancers." (PMID 36558554, 2022). "The Western blot analysis showed that 40 induced caspase-mediated apoptosis of BEL-7402 cancer cells, related to the increase and decrease of Bax and Bcl-2 expressions, respectively." (PMID 35209235, 2022).
cancer (continued). "BCL-2, whose gene families played pivotal roles in the programmed cell death regulations, induces apoptosis evasion and drug resistance evolution in cancers." (PMID 35174150, 2022). "BH3 mimetics neutralize the antiapoptotic function of Bcl-2 proteins and are highly promising compounds inducing apoptosis in several cancer entities including pediatric malignancies." (PMID 35013156, 2022). "Of these, multi-tyrosine kinase inhibitor Sunitinib and B-cell lymphoma 2 (BCL-2) inhibitor Venetoclax had a selective effect for cancer organoids, inhibiting two of the CCAO lines, but leaving the third CCAO line unharmed." (PMID 35764936, 2022). "BCL2 is upregulated in the majority of cancer cells of different origins and can impact the survival of cells treated with various anticancer drugs." (PMID 36361596, 2022). "Overexpression of the BCL2 protein has been reported in many cancers, including lung, where it acts as a key player in cancer, favoring survival by suppressing cell death." (PMID 35370727, 2022). "Our findings define tBID as an effector of mitochondrial permeabilization in apoptosis and provide a new paradigm for BCL‐2 proteins, with implications for anti‐bacterial immunity and cancer therapy." (PMID 34931711, 2022). "The oncogenic BCL2 protein, commonly overexpressed in various cancers, promotes cell survival by evading apoptosis." (PMID 35645336, 2022). "One of the important findings in cancer studies is that the ratio of pro-apoptotic (Bax) to anti-apoptotic (Bcl-2) proteins can be a key checkpoint in the common portion of the cell death signal pathway." (PMID 35163851, 2022). "Among these eight cancer targets, BCL-2, Topoisomerase, PTK, mTOR and PI3K docking studies showed the best binding energy inhibition constant and ligand efficiency.Thus, it concludes lupeol is one of the significant anticancer phytodrugs." (PMID 36518133, 2022). "TQ has been shown to inhibit cancer cell proliferation; arrest cancer cell cycle progression; and, induce pro-apoptotic effects with the targets of Bcl-2, caspases, PPArs, NF-kB, STAT3, MAPK, Akt and ROS16." (PMID 35246558, 2022). "Studies have also shown that phloretin induces apoptosis in cancer cells via the inhibition of Bcl-2 levels and a decrease in the phosphorylation of c-Jun N-terminal kinase (JNK) and p38 MAPK." (PMID 36557950, 2022). "In comparison to the anti-cancer drug fluorouracil, Chr and EM both demonstrated better binding scores against the protein targets caspase-3, apoptosis regulator Bcl-2, TNIK, and CDK2." (PMID 36355520, 2022). "SS-TP LPs were confirmed to be internalized and accumulated into the mitochondria of cancer cells in a time-dependent manner, followed by triggering permeabilization of the mitochondrial outer membrane by inhibiting Bcl-2." (PMID 36212077, 2022). "We found that capsaicin induced apoptosis in cancer cells by suppressing the expression of the mutant Bcl-2 gene." (PMID 35865422, 2022). "Studies have shown the downregulation of Beclin 1 and upregulation of Bcl-2 in many types of cancers, both were closely related to poor prognosis." (PMID 36676047, 2022). "The ability of butyrate to de-repress epigenetically silenced genes in cancer cells, such as cell cycle inhibitor p21 and the pro-apoptotic protein Bcl-2, has important implications for cancer prevention and therapy." (PMID 36144335, 2022). "The BH3-mimetic venetoclax blocks the anti-apoptotic B-cell lymphoma-2 (Bcl-2) protein and thereby induces apoptosis in cancer cells." (PMID 35385564, 2022).
cancer (continued). "The Bcl-2/Bax/caspase-3 signaling pathway is the downstream target of NF-κB, and plays an important role in cancer cells apoptosis." (PMID 36286423, 2022). "Studies have shown that AURKB inhibited the intrinsic resistance of malignant tumors to autophagy-related death by overcoming Bcl-2 expression." (PMID 36561847, 2022). "TLPE extract also caused a decrease in the level of the anti-apoptotic protein Bcl2 in both cancer cell lines when tested at higher concentrations." (PMID 36540797, 2022). "Considering the critical role of anti-apoptotic BCL-2 proteins in apoptosis resistance by cancer cells, selective drugs designed to inhibit anti-apoptotic BCL-2 proteins, termed BH3 mimetics, have been developed." (PMID 35256598, 2022). "Numerous studies have revealed that curcumin triggers apoptosis through BAX/BCL-2 mediated pathway in cancer cells." (PMID 35566271, 2022). "BAX/BCL-2 ratio is among the most widely studied and reported protein expression pattern for assessment of apoptotic cancer cell death aimed to determine the eventual outcome, leading to apoptosis or survival." (PMID 35408514, 2022). "This way, we provide a unique residue- and domain-specific insight into the molecular functioning of Bcl-2 at the membrane level, an insight also opening up for interfering with this cell-protecting mechanism in cancer therapy." (PMID 36325615, 2022). "On the other hand, the pro-apoptotic effect of Nur77 involves its translocation from the nucleus to mitochondria, where it interacts with Bcl-2 and converts Bcl-2 from a survival to a killer of cancer cells." (PMID 36686679, 2022). "Venetoclax is a new type of BH3 mimetic compound that can target the binding site in the BCL-2 protein and induce apoptosis in cancer cells by stimulating the mitochondrial apoptotic pathway." (PMID 35598030, 2022). "Due to its central role in mitochondrial apoptosis, Bcl-2 inhibition is considered to induce a malfunctioning apoptosis pathway, which is one of the most common ways for cancer cells to escape death." (PMID 36309485, 2022). "The isatin sulfonamide derivatives showed an ability to depress the action of the survival mechanism of Bcl-2, inhibiting angiogenesis, and further hindering cancer invasion through inhibition of uPA and heparanase expression." (PMID 35327524, 2022). "BCL-2, whose gene families play pivotal roles in the programmed cell death regulations, induces apoptosis evasion and drug resistance evolution in cancers." (PMID 35174150, 2022). "It is well-known that NF-κB signaling regulates apoptotic cancer cell death through the activation of the BCL-2 anti-apoptotic gene family, such as BCL-2, Cellular Inhibitor of apoptosis Protein 1/2 (cIAP1/2)." (PMID 35884618, 2022). "We obtained the synergy scores data for the inhibitors of AKT and BCL2 in three cell lines that matched to our 17 distinct cancer networks (upper left)." (PMID 36071176, 2022). "This view was documented by silencing STAT3 gene which induced a strong suppression of total p‐STAT3 and Bcl‐2 protein levels, and a dramatic reduction of transcriptional levels of cancer‐related cytokines, genes and cell survival." (PMID 34850540, 2022). "Venetoclax has been shown to be effective in xenograft models of human lymphoid tumors that overexpress Bcl-2, a crucial protein for the survival of these cancers." (PMID 35053443, 2022). "Dual silencing of Bcl-2 and survivin by an oHSV-1 vector demonstrates antitumor efficacy in cancer cells." (PMID 35806132, 2022). "Apoptosis is a key trait deregulated in cancer and is regulated by two families of proteins: the B-cell leukemia/lymphoma 2 (BCL2) family and the inhibitor of apoptosis protein (IAP) family." (PMID 35053500, 2022).
cancer (continued). "It has been reported that CCM can promote the apoptosis cascade particularly through the downregulation of BCL-2 in different cancer cell types." (PMID 36155114, 2022). "And in chronic lymphocytic leukemia, after the appearance of acquired resistance of venetoclax, the inhibitor of B-cell lymphoma-2 (BCL-2), mitochondrial mass of cancer cells and OXPHOS increased and OXPHOS inhibition rescued the venetoclax sensitivity." (PMID 35174150, 2022). "One of the master regulators of apoptosis is BCL-2, which prevents cells from entering apoptosis and is therefore highly expressed in most cancer cells." (PMID 36089606, 2022). "Bcl2 is an antiapoptotic protein which regulates cancer cell survival by altering the pro-apoptotic/antiapoptotic balance in the cell and promotes angiogenesis." (PMID 35885991, 2022). "In OV, MSI1 acted as an oncogene, inducing phosphorylation of ERK protein, activating the expression of anti-apoptotic protein Bcl-2, and promoting migration and invasion of cancer cells." (PMID 35980273, 2022). "Studies have confirmed the feasibility of using the regulatory miR-15/16 of Bcl-2-associated X protein (BAX)/Bcl-2 homologous antagonist killer (BAK)-dependent pathway, the classical pathway of Bcl-2, to fight cancer." (PMID 35359956, 2022). "Bcl-2 and other anti-apoptotic family members have been found to be over-expressed in a variety of cancers." (PMID 36539401, 2022). "Such transformation favours cancer onset and progression via the TNF-α-induced release of cytokines and angiogenic factors as well as anti-apoptotic factors such as (B-cell CLL/lymphoma 2 (BCL-2)) and cyclin D1 and cyclin E in cancer cells." (PMID 35328822, 2022). "ERK1/2 signaling can regulate BCL-2 proteins, which regulate numerous vital processes such as cell cycle progression, migration, and survival dysregulation that are cancer's hallmarks." (PMID 36443682, 2022). "As many of the upstream pathways that regulate expression of the BCL-2 family are disrupted in cancer, direct targeting of pro-survival BCL-2 proteins is an attractive way to restore apoptosis." (PMID 35349392, 2022). "Elevated levels of BCL-2, pro-survival factor, are a marker of pathogenesis for many diseases including cancer and human immunodeficiency virus type 1 (HIV-1)." (PMID 36569952, 2022). "Berberine hydrochloride inhibited the proliferation and apoptosis of cancer cells was induced (cell viability was lowest for 215.164 μM berberine hydrochloride treatment), possibly through the downregulation of Bcl-2." (PMID 36144625, 2022). "Cells sensitive to pan-BCL-2 inhibition, in particular cancer cells, are normally primed to apoptose due to elevated levels of the pro-apoptotic factor Noxa20,21." (PMID 36564381, 2022). "Re-activation of PI3K/AKT is the key reason for the resistance of BCL-2 inhibitor treatment in cancer." (PMID 36232694, 2022). "On the other hand, Bcl-2, NF-κB, and Akt-mTOR are antiapoptotic factors, which are down-regulated in a combination treatment of HT and anti-cancer drugs or natural products." (PMID 35453310, 2022). "Studies have shown that PI3K/AKT phosphorylation inhibits Bax activity and promotes the release of Bcl-2, which confirms the potential therapeutic effect of this bacterium as an anti-cancer drug." (PMID 36559282, 2022). "BCL-2 is not only involved in the neoplastic development, but also in the resistance mechanism to cancer treatment." (PMID 35890348, 2022). "Cancer cells escape apoptosis by a variety of mechanisms, including increased production of pro-survival proteins (BCL2, BCLXL, or MCL1)." (PMID 35945614, 2022). "Most of the pulmonary tuft cell-like cancers of Cohort-J strongly expressed BCL2 and KIT protein, and the percentages of immunoreactive cells were significantly higher in the tuft cell-like than non-tuft cell-like groups (P < 0.05)." (PMID 36402755, 2022).
cancer (continued). "In this context, the therapies pointed at BCL-2 inhibition can be considered crucial to overcome resistance to the common strategies for cancer treatments." (PMID 35890348, 2022). "API depletes anti-apoptotic Bcl2 and increases pro-apoptotic caspase 3 whereas miR-155 increases anti-apoptotic Bcl2 and decreases pro-apoptotic caspase 3 in cancer cells." (PMID 35892872, 2022). "Recent studies have shown that luteolin regulates cyclin D1, cyclin E, p21, and Bcl2, resulting in the prevention of cancer development in gastric cancer." (PMID 35956766, 2022). "EGCG degraded PARP by downregulating P-Akt, Bcl-2, and P-gp, suppressing the vitality of drug-resistant cancer cells and decreasing the stemness of tumor cells, resulting in more sensitivity of cancer cells to TMZ and apoptosis." (PMID 36545470, 2022). "Neferine caused inhibition of cell proliferation and induced apoptosis through decreased cell viability by lowering levels of Bcl-2, which promoted apoptosis of cancer cells." (PMID 35805049, 2022). "Performing this approach, we identified two inhibitors showing high affinity for recombinant Bcl-2, Bcl-xL and Mcl-1 proteins and in vitro/in vivo anti-tumoral activity in preclinical cancer models with different histotype." (PMID 35265218, 2022). "In various cancer cell models, disrupting the complex between IP3Rs and Bcl-2 was even sufficient to provoke cell death through Ca2+ overload." (PMID 34750538, 2022). "Cancer cells can develop resistance to BCL-2 inhibitors by increasing the expression of another anti-apoptotic protein, MCL-122–26." (PMID 36564381, 2022). "STAT3 and its downstream effectors, such as Survivin and Bcl-2, regulate multiple processes that are critical for cancer development, involving tumorigenesis and growth, cell death, cellular senescence, metastasis, and differentiation." (PMID 36276282, 2022). "Obatoclax is a pan-antagonist of the BCL-2 protein family (i.e., the BCL-2, -xl, and -w plus Mcl-1) which are over-expressed in numerous cancer types." (PMID 35734783, 2022). "Antiapoptotic Bcl-2 contributes to cancer formation and progression by promoting the survival of altered cells." (PMID 36077992, 2022). "Further, we validated the anti-cancer and anti-BCL-2 effects of SM396, SM216, and SM949 along with the initial library (26 compounds) by various in vitro and in vivo assays to identify the mechanisms of the identified BH4 selective inhibitors." (PMID 36358660, 2022). "AT-101, a natural Bcl-2 homology domain 3 (BH3) mimetic, is a small molecule inhibitor that downregulates anti-apoptotic Bcl-2 and Bcl-2-related proteins in human cancer cells." (PMID 35215257, 2022). "We have synthesised a small molecule inhibitor against Bcl2, Disarib, which exhibited cytotoxicity in Bcl2 ‘high’ cancer cell lines and CLL patient primary cells." (PMID 35885991, 2022). "Frequently, cancer cells upregulate anti-apoptotic BCL-2 family members to inhibit pro-apoptotic BCL-2 members BAX, BAK, and BH3-only proteins, thus blocking apoptosis." (PMID 35256598, 2022). "The highly selective molecular disruptor, Venetoclax, prevents the binding of prosurvival proteins like BAX or BAK from binding to BCL2, thereby reactivating apoptotic signaling pathways in BCL2 overexpressing cancers." (PMID 36328247, 2022). "Cathepsin B and Cathepsin D release into the cytosol promoted the cleavage and activation of BID, and Dcf1 also decreased the expression of Bcl‐2 to induce the release of proapoptotic factors and enhance the levels of cancer suppressors." (PMID 34799992, 2022).